FGF11 (fibroblast growth factor 11)
Diseases named in the same sentence as FGF11 in open-access papers (continued):
Sharing a sentence is not in itself a finding about the gene and the disease.
tumor (continued). "In contrast, the overexpression of FGF11 not only promoted the tumor growth rate, but also increased the percentage of cells expressing Ki-67 in the tumor tissues." (PMID 34404435, 2021). "It was also discovered that miR-24-3p directly targets FGF11 for its activity, while tumor FGF11 levels were positively correlated to CD4+ and CD8+ T cell counts in vivo, which were predicative of favorable patient disease-free survival." (PMID 34680611, 2021). "In this study, we first confirmed the upregulation of FGF11 in both NSCLC tumor tissues and NSCLC cell lines, suggesting an oncogenic effect of FGF11." (PMID 34404435, 2021). "In addition, patients whose tumours had a weaker FGF11 immunoreactivity than the adjacent normal epithelium were all alive at followup (n = 4)." (PMID 37046615, 2023). "The GeneMANIA and STRING databases were used to search for genes that interact with FGF11, and the Tumor Immune Estimation Resource (TIMER) database was used to discover connections between FGF11 and immune cells, as well as any correlations with immune-related genes." (PMID 37250453, 2023). "FGF11 may increase tumor cell immune escape by increasing T cell exhaustion in the LUAD tumor microenvironment, contributing to the poor prognosis for patients with LUAD." (PMID 37250453, 2023). "FGF11 was found to be substantially expressed in most tumor tissues after pan-cancer investigation." (PMID 37250453, 2023). "Fibroblast growth factor 11 (FGF11) accelerates tumor proliferation in a variety of cancer types." (PMID 37250453, 2023). "FGF11 was searched in the Tumor Cancer Genome Atlas (TCGA) and ImmProt databases." (PMID 37250453, 2023). "Researchers reported that FGF11 acts as a novel modulator of hypoxia-induced tumor progression." (PMID 34315402, 2021). "FGF11 was upregulated in NSCLC tumor tissues and tumor cell lines." (PMID 34404435, 2021). "Moreover, immunohistochemistry (IHC) analysis confirmed a higher protein level of FGF11 NSCLC tumor tissue." (PMID 34404435, 2021). "Moreover, FGF11 knockdown suppressed NSCLC tumor growth whereas FGF11 overexpression promoted tumor growth in vivo." (PMID 34404435, 2021). "Our study showed that FGF11 functions as an oncogene in tumor NSCLC progression." (PMID 34404435, 2021). "Furthermore, the data imply that FGF11 may play a major role in the prognosis of patients with these tumours." (PMID 37046615, 2023). "Thus, by decreasing immune cell infiltration and restricting the immune anticancer activity, FGF11 may play a role in increasing tumor cell immune escape in the tumor microenvironment of LUAD." (PMID 37250453, 2023). "Finally, the functional role of FGF11 in NSCLC tumor growth was evaluated by in vivo study." (PMID 34404435, 2021). "These cells secrete FGF11 to activate the FGFR1 signalling pathway, thereby promoting the expansion of tumour stem-like cells and showing a strong correlation with T cell exhaustion." (PMID 40630800, 2025). "FGF11 activates the FGFR1 signaling pathway in adjacent tumor cells, forming a pro-tumorigenic feedback loop that promotes tumor proliferation and stemness." (PMID 41002423, 2025). "FGF11 was significantly upregulated in PTC under high iodine exposure, and its overexpression promoted tumor cell proliferation, invasion, migration, and inhibited apoptosis." (PMID 38902782, 2024). "Likewise, when comparing the fraction (percentage) of FGF11 positive tumour cells, patients with a higher fraction of FGF11 positive cells (>75%) had a significantly worse OS, compared to those with fewer positive tumour cells (58% vs. 83%, log rank, p = 0.047)." (PMID 37046615, 2023). "For example, FGF11 and FGF 14 are members of the fibroblast growth factor (FGF) family, which are ligands of FGF receptors (FGFR) and involved in tumor proliferation, migration, and invasion." (PMID 34083586, 2021).
tumor (continued). "Through the microRNA target scan of FGF11 and experimental validation, we found that miR-525-5p negatively regulates FGF11 expression in NSCLC cells, suggesting a tumor-suppressor role of miR-525-5p in the proliferation and migration of NSCLC cells." (PMID 34404435, 2021). "In detail, FGF1 and FGF10 were downregulated in most of the tumor types whereas FGF3, FGF5, FGF11, FGF19, FGF20, and FGF21 were upregulated in most of the tumor types." (PMID 32596330, 2020). "The result showed that miR-525-5p expression level was significantly lower in NSCLC tumor tissues when compared to normal tissues, and there was a negative correlation between miR-525-5p level and FGF11 level." (PMID 34404435, 2021). "Transmembrane protein 108 (TMEM108), C3orf47 and coenzyme Q8A (CABC1) were the top three genes positively correlated with tumor grade, whereas ladinin 1 (LAD1), TIAF1 and FGF11 were the top three genes negatively correlated with the tumor grade of ESCC patients." (PMID 28904855, 2017). "However, the difference in survival was not significant when comparing patients with weaker tumour to normal epithelium FGF11 expression to those patients with a stronger tumour to normal epithelium FGF11 expression." (PMID 37046615, 2023). "TMEM108 and C3orf47 were positively correlated with tumor grade and eight genes, including LAD1, TIF1, FGF11, carbonic anhydrase 12 (CA12), G protein subunit α15 (GNA15), junction plakoglobin (JUP), plakophilin 1 (PKP1) and PPARD, were negatively correlated with the tumor grade of ESCC patients." (PMID 28904855, 2017). "Additionally, we suggest that targeting the circ_0004851/miR-296-3p/FGF11 axis is a potential strategy for the treatment of PTC, and that circRNA silencing through the ceRNA mechanism could play a crucial therapeutic role in resisting high iodine-promoted tumor progression." (PMID 38902782, 2024).
cancer (9 papers, 2018 to 2024). A tumor composed of atypical neoplastic, often pleomorphic cells that invade other tissues. "At present, the prognostic role of FGF11 was only reported in rare cancers, such as nasopharyngeal carcinoma and prostate cancer." (PMID 34404435, 2021). "Although FGF11 has been identified as an oncogene in a number of cancer types, its function in PTC is unknown." (PMID 38902782, 2024). "These outcomes indicate a significant upregulation of FGF11 gene expression in response to high iodine exposure, and its presence across various malignant tumors implies that FGF11 could serve as a pivotal function in iodine-induced PTC development." (PMID 38902782, 2024). "Hypoxia pathway is dysregulated in many cancers, and we next attempted to investigate whether the oncogenic function of FGF11 is related to hypoxia signaling pathway." (PMID 34404435, 2021). "Fgf11 is highly expressed in cancers and enhances cancer growth." (PMID 29323161, 2018). "Repeated analysis in second human cancer cell line, A549, uncovers cell type specific responses, with 2 out the 6 sites studied (CA9 and FGF11 promoters) only displaying accessibility sensitivity to hypoxia in HeLa cells." (PMID 35258521, 2022). "However, the functional role of FGF11-HIF-1α axis in cancer development remains unclear." (PMID 34404435, 2021).
infection (1 paper, 2021). The state of being infected such as from the introduction of a foreign agent such as serum, vaccine, antigenic substance or organism. "To further support a role of FGF11 in promoting NSCLC cell proliferation, we overexpressed FGF11 in A549 and NCI-H460 cells by infection with lentivirus carrying FGF11 cDNA clone." (PMID 34404435, 2021). "FGF11 was silenced in A549 and NCI-H460 cells by infection with FGF11 shRNA (shFGF11) lentivirus." (PMID 34404435, 2021).
FGF11 also shares sentences with these, for which no sentence is quoted: renal fibrosis (3 papers); diabetic kidney disease (2); brain tumor (1); metabolic disorders (1); myxoid liposarcoma (1); Oropharyngeal Squamous Cell Carcinoma (1); psoriasis (1); rheumatoid arthritis (1).